ARHGAP24 (Rho GTPase activating protein 24)
Description:
Rho GTPase-activating protein involved in cell polarity, cell morphology and cytoskeletal organization. Acts as a GTPase activator for the Rac-type GTPase by converting it to an inactive GDP-bound state. Controls actin remodeling by inactivating Rac downstream of Rho leading to suppress leading edge protrusion and promotes cell retraction to achieve cellular polarity. Able to suppress RAC1 and CDC42 activity in vitro. Overexpression induces cell rounding with partial or complete disruption of actin stress fibers and formation of membrane ruffles, lamellipodia, and filopodia. Isoform 2 is a vascular cell-specific GAP involved in modulation of angiogenesis.
Synonyms: FilGAP; RC-GAP72; DKFZP564B1162; FLJ33877; RCGAP72; p73; p73RhoGAP
Tractability: Antibody: the Human Protein Atlas places it where antibodies can reach. PROTAC: its protein half-life has been measured.
Gene: Protein-coding gene on chromosome 4 (85,475,150 to 86,002,668, forward strand). Ensembl gene ENSG00000138639.
Subcellular location: Cytoplasm, cytoskeleton; Cell junction, adherens junction; Cell junction, focal adhesion; Cell projection
Subcellular location (Human Protein Atlas): Cytosol; Plasma membrane
Pathways (Reactome):
Signal Transduction: CDC42 GTPase cycle; RAC1 GTPase cycle; RHOA GTPase cycle
Gene Ontology:
Molecular function: protein binding; GTPase activator activity
Biological process: negative regulation of Rac protein signal transduction; negative regulation of ruffle assembly; wound healing, spreading of epidermal cells; regulation of small GTPase mediated signal transduction; signal transduction
Cellular component: focal adhesion; adherens junction; cytoskeleton; plasma membrane
Genetic constraint (gnomAD): Loss-of-function variants: 49 observed, 78.02 expected, observed/expected ratio (o/e) 0.63, 90% interval 0.5 to 0.8. The upper end of that interval is the gene's LOEUF score, 0.8, which puts it in group 3 of 6, group 1 being the genes least tolerant of losing a copy. Missense variants: 929 observed, 960.76 expected, observed/expected ratio (o/e) 0.97, 90% interval 0.92 to 1.02. Synonymous variants: 345 observed, 341.66 expected, observed/expected ratio (o/e) 1.01, 90% interval 0.92 to 1.1.
Homologues: Orthologues: chimpanzee ARHGAP24 (99% identical), macaque ARHGAP24 (97% identical), dog ARHGAP24 (96% identical), rabbit ARHGAP24 (94% identical), rat Arhgap24 (93% identical), guinea pig ARHGAP24 (93% identical), mouse Arhgap24 (93% identical), pig ARHGAP24 (93% identical), tropical clawed frog arhgap24 (79% identical), zebrafish arhgap24 (72% identical). Paralogues in human: ARHGAP22 (44% identical), ARHGAP25 (34% identical).
Diseases named in the same sentence as ARHGAP24 in open-access papers:
ARHGAP24 is named in the same sentence as 52 diseases in open-access papers, as found by Europe PMC text mining. Sharing a sentence is not in itself a finding about the gene and the disease. The quoted sentences say what the papers report.
breast carcinoma (9 papers, 2016 to 2024). "ARHGAP24 also inhibited the growth of kidney cancer, breast cancer, and astrocytoma, and its low expression can be used as a predictor of poor prognosis in patients with these tumors 13-15." (PMID 36168627, 2022). "Several studies reported ARHGAP24 as a tumor suppressor gene in various malignant tumors, including malignant lymphomas, breast cancer, renal cancer, lung cancer, and colorectal cancer." (PMID 34179011, 2021). "Moreover, ARHGAP24 affects the STAT3 signaling pathway, which modulates the anti-cancer activity of sorafenib against breast cancer." (PMID 35812178, 2022).
renal cell carcinoma (6 papers, 2021 to 2025). "Interestingly, low ARHGAP24 was also associated with shorter OS in patients with other tumors, such as renal cell carcinoma (P < 0.001), lung cancer (P < 0.05) and pancreatic ductal adenocarcinoma (P = 0.045), suggesting its common inhibitory role in tumors." (PMID 36168627, 2022). "ARHGAP24 was reported to inhibit cell cycle progression, induces apoptosis, and suppresses invasion in renal cell carcinoma." (PMID 34073601, 2021). "By contrast, ARHGAP24 (FilGAP) emerged as a tumor-suppressor in renal cell carcinoma by inhibiting G1/S phase cell cycle progression, increasing apoptosis, and inhibited tumor growth." (PMID 34493786, 2021).
focal segmental glomerulosclerosis (5 papers, 2017 to 2025). A renal disorder characterized by sclerotic lesions in the glomeruli. "For examples, Q158R mutation of ArhGAP24 (FilGAP) found in focal segmental glomerulosclerosis causes loss of Rac1-GAP activity." (PMID 40632829, 2025). "For instance, the Rac1-GAP ARHGAP24 knock-down in podocytes increased membrane ruffling, while a loss-of-function mutation in the ARHGAP24 gene was associated with hereditary focal segmental glomerulosclerosis (FSGS), a kidney disease characterized by podocyte dysfunction." (PMID 41306285, 2025). "For example, human gene mutations in Rac1 regulatory proteins, ARHGAP24 and ARGHDIA, have been reported to alter Rac1 activity and are associated with focal segmental glomerulosclerosis; more so, recent evidence suggests that these disturbances are implicated in minimal change disease." (PMID 28880939, 2017).
lung carcinoma (4 papers, 2020 to 2022). "ARHGAP24 also inhibited the activation of signal transducer and activator of transcription 6 signaling in lung cancer cells and induced tumor cell apoptosis and inhibited cell proliferation through the WWP2/p27 pathway." (PMID 36168627, 2022). "ARHGAP24 inhibits cell proliferation and cell cycle progression and induces apoptosis of lung cancer." (PMID 32624706, 2020). "Silencing of ARHGAP24 activates the β-catenin signaling pathway to promote lung cancer cell migration and invasion." (PMID 32624706, 2020).
glioma (3 papers, 2016 to 2023). A benign or malignant brain and spinal cord tumor that arises from glial cells (astrocytes, oligodendrocytes, ependymal cells). "Overall FilGAP (ARHGAP24) expression was significantly decreased in glioblastoma (IV) compared to lower grade glioma (II and III)." (PMID 38065968, 2023).
Bladder Cancer (2 papers, 2021 to 2023). "ARHGAP5, ARHGAP17 and ARHGAP24 promoted bladder cancer progression by establishing a tumor-promoting microenvironment or cellular mechanical property-mediated cell motility." (PMID 37175461, 2023).
liver cancer (2 papers, 2022 to 2023). An epithelial or non-epithelial malignant neoplasm that arises from the liver. "The latest study found that tumor suppressor gene Rho-GTPase-activating protein 24 (ARHGAP24) can inhibit liver cancer cell proliferation, induce liver cancer cell G0/G1 phase arrest, and inhibit liver cancer cell invasion and migration." (PMID 37861491, 2023).
pancreatic cancer (2 papers, 2021 to 2022). "Using the Oncomine database the results demonstrated that the mRNA expression levels of ARHGAP24 are downregulated in pancreatic cancer." (PMID 35812178, 2022). "Furthermore, Smad3's β4 region-dependent downregulation of ARHGAP24 and ARHGAP27 was also observed in PANC-1 human pancreatic cancer cells." (PMID 33741342, 2021). "There is no research on the role of ARHGAP24 protein in pancreatic cancer." (PMID 35812178, 2022).
renal carcinoma (2 papers, 2021). A carcinoma arising from the epithelium of the renal parenchyma or the renal pelvis. "Arhgap24, regulates cell cycle progression and proliferation in lung and renal cancer, whereas Svil promotes cell proliferation and survival through regulation of cytokinesis and amplification of stimulus-mediated signaling in various cells." (PMID 34663679, 2021).
triple-negative breast carcinoma (2 papers, 2022). An invasive breast carcinoma which is negative for expression of estrogen receptor (ER), progesterone receptor (PR), and human epidermal growth factor receptor 2 (HER2). "For example, previous studies have reported that ARHGAP24 suppresses cell invasion in triple-negative breast cancer." (PMID 35812178, 2022). "In addition, activation of the RASAL2/ARHGAP24/RAC1 module slows triple-negative breast cancer (TNBC) progression, and RASAL2 overexpression is related to poor prognosis and tumor recurrence in TNBC." (PMID 36159573, 2022).
Arrhythmia (1 paper, 2024). Any cardiac rhythm other than the normal sinus rhythm. "GWAS identified genetic associations primarily related to cardiac conduction and arrhythmia but also identified a potentially novel association with ARHGAP24, which may be a pathway warranting further investigation." (PMID 39540287, 2024).
asthma (1 paper, 2022). "Upregulated in the blood of severe asthma and PTSD subjects were mRNA encoding Syntaxin 8 (STX8), and Rho GTPase Activating Protein 24 (ARHGAP24)." (PMID 36206293, 2022).
cardiomyopathy (1 paper, 2023). A disease of the heart muscle or myocardium proper. "They observed an increase promoter methylation of three genes associated with cardiac angiogenesis in cardiomyopathy, PECAM1, ARHGAP24, and AMOTL2, suggesting that DNA methylation induces altered gene expression in cardiomyopathy." (PMID 37008904, 2023).
chronic hepatitis B virus infection (1 paper, 2025). Chronic form of hepatitis B infection. "Polymorphisms in the ARHGAP24 gene have been shown to influence growth traits in pigs and the progression of chronic hepatitis B virus infection in the Han Chinese population." (PMID 40498520, 2025).
cognitive decline (1 paper, 2025). "Other clusters, such as ARHGAP24+ oligodendrocytes, were consistently higher in individuals with steeper slope of cognitive decline in both studies, though not reaching statistical significance (p<0.05)." (PMID 40584839, 2025).
colon cancer (1 paper, 2015). "These experiments also confirmed that gene expression of ARHGAP24 is highly elevated among the PMP lines compared with the 5 colon cancer cell lines." (PMID 25929336, 2015). "We thus compared with the same gene expressions (up-regulated transcripts: SLC16A4, DSC3, ALDOB, EPHX4, ARHGAP24; and down-regulated transcripts (MS4A12, TMIGD1, CASP5) in 5 colon cancer lines: HCT 116, Caco2, HT-29, Lovo, and C32." (PMID 25929336, 2015).
colorectal tumors (1 paper, 2015). "However, three transcripts (SKAP1, ARHGAP24, and NT5E) were up-regulated in PMP but generally down-regulated in colorectal tumors." (PMID 25929336, 2015).
congenital heart disease (1 paper, 2024). A heart disease that is present at birth. "Although shared genes like TMTC1, ART3, and ARHGAP24 are shown to contribute to different congenital heart disease subtypes, they actually play different roles across subtypes." (PMID 39202774, 2024). "For instance ARHGAP24 contributes to various subtypes of congenital heart disease, including dilated cardiomyopathy, hypertrophic cardiomyopathy, and HF-hypoplastic left heart syndrome." (PMID 39202774, 2024). "Considering that ARHGAP24 can participate in the rho GTPase-activating process, different roles of ARHGAP24 across different congenital heart diseases indicate different roles of rho GTPase activation across different disease subtypes." (PMID 39202774, 2024). "However, ARHGAP24 plays different roles during the pathogenesis of three subtypes of congenital heart diseases." (PMID 39202774, 2024). "Apart from ARHGAP24, PTEN, as another predicted gene contributing to congenital heart disease, has also been mentioned to contribute to neohypoplastic left heart syndrome at both transcriptomics (gene expression profiling, as shown in this study) and genetics levels." (PMID 39202774, 2024).
dementia (1 paper, 2025). Loss of intellectual abilities interfering with an individual's social and occupational functions. "Among the three dementia-predominant subgroups, Group 4 was characterized by higher proportions in a subset of glutamatergic neuron clusters, as well as ARHGAP24+ oligodendrocytes." (PMID 40584839, 2025).
depression (1 paper, 2022). "In addition, previous studies have found that the ARHGAP24 gene is associated with human depression and childhood autism accompanied by aggressive behavior." (PMID 35433684, 2022). "ARHGAP24 has been found to be a genetic marker to distinguish patients with major depression from healthy people." (PMID 35433684, 2022).
dilated cardiomyopathy (1 paper, 2024). Cardiomyopathy which is characterized by dilation and contractile dysfunction of the left and right ventricles. "In cardiomyocytes, distinct genes such as TMTC1, ART3, ARHGAP24, SHROOM3, and XIST were linked to dilated cardiomyopathy, Neo-Hypoplastic Left Heart Syndrome, hypertrophic cardiomyopathy, HF-Hypoplastic Left Heart Syndrome, and Tetralogy of Fallot, respectively." (PMID 39202774, 2024).
hepatocellular carcinoma (1 paper, 2022). A malignant tumor that arises from hepatocytes. "However, no study has systematically investigated the clinical significance of RhoGAPs and analyzed the functions of ARHGAP24 in hepatocellular carcinoma (HCC)." (PMID 36168627, 2022).
HIV-1 infection (1 paper, 2025). The type species of lentivirus and the etiologic agent of acquired immunodeficiency syndrome (AIDS). "MDDCs transduced with shRNA targeting both ARHGAP24 and ARF6 (another small GTPase) showed increased susceptibility to HIV-1 infection." (PMID 40029073, 2025). "FNBP1L, ARHGAP24, and ATP6V1B1 knockdown repeatedly proved to increase HIV-1 infection in additional donors, confirming screening observations." (PMID 40029073, 2025). "Over a 7-day period in THP1 cells, knockdown of FNBP1L, ARHGAP24, and ATP6V1B1 resulted in sustained enhancement of HIV-1 infection." (PMID 40029073, 2025). "From this group, the actin cytoskeleton regulators FNBP1L and ARHGAP24, along with the vacuolar proton pump ATP6V1B1, were prioritized for further study due to their strong impact and lack of prior association with HIV-1 infection in the literature." (PMID 40029073, 2025). "In a selective, shRNA-mediated knockdown screen in primary monocyte-derived dendritic cells (MDDCs) infected with HIV in the presence of SAMHD1-disactivating Vpx containing virus-like particles, three proteins hampering HIV-1 infection were identified: FNBP1L, ARHGAP24, and ATP6V1B1." (PMID 40029073, 2025). "Depletion of FNBP1L, ARHGAP24, and ATP6V1B1 showed increased entry rates upon HIV-1 infection." (PMID 40029073, 2025). "Knocking down FNBP1L, ARHGAP24, and ATP6V1B1 in CD4+ T cells did not enhance HIV-1 infection, contrasting sharply with the significant effects observed in MDDCs." (PMID 40029073, 2025). "Our results show that the depletion of FNBP1L, ARHGAP24, and ATP6V1B1 enhances HIV-1 infection in MDDCs, but not in CD4+ T cells." (PMID 40029073, 2025).
hypertrophic cardiomyopathy (1 paper, 2024). A condition in which the myocardium is hypertrophied without an obvious cause. "A common variants analysis of complex diseases revealed that ARHGAP24 (Rho GTPase Activating Protein 24, 610586)-associated variants are functionally associated with hypertrophic cardiomyopathy, validating our predicted rules." (PMID 39202774, 2024). "For instance, genetic variants on ARHGAP24 have been recognized as contributing to the pathogenesis of hypertrophic cardiomyopathy." (PMID 39202774, 2024). "ARHGAP24 is up-regulated in hypertrophic cardiomyopathy while down-regulated in HF-hypoplastic left heart syndrome." (PMID 39202774, 2024).
ovarian carcinoma (1 paper, 2020). A malignant neoplasm originating from the surface ovarian epithelium. "And miR-106a-5p promoted ovarian cancer progression by targeting ARHGAP24, while lncRNA HOTAIRM1 sponged miR-106a-5p and inhibited ovarian cancer development." (PMID 33290256, 2020).
sarcoma (1 paper, 2024). A usually aggressive malignant neoplasm of the soft tissue or bone. "Interestingly, cytoskeleton proteins, including RASA1, RASAL2, NCKAP5, MACF1 and ARHGAP24, were reduced following differentiation, indicating that the sarcoma microenvironment induces resident‐like myeloid cell transfer." (PMID 39658531, 2024).
thyroid tumor (1 paper, 2021). A benign or malignant neoplasm affecting the thyroid gland. "However, no study was performed on the functions of ARHGAP24 in thyroid tumors so far." (PMID 34179011, 2021).
tumor (18 papers, 2013 to 2024). "Liquid chromatography-tandem mass spectrometry, co-immunoprecipitation, GTPase activation, ubiquitination, and luciferase reporter assays and bioinformatics analysis were carried out to gain insights into the mechanisms underlying the tumor-suppressive function of ARHGAP24." (PMID 36168627, 2022). "Previous studies reported that ARHGAP24 was a Rac-specific RhoGAP, inactivating Rac1 and thereby inhibiting tumor progression." (PMID 36168627, 2022). "RhoGAP 24 (ARHGAP24) is a member of the RhoGAP protein family 9-10 with strong tumor suppressor potential." (PMID 36168627, 2022). "Univariate Cox regression analysis showed that ARHGAP24, tumor size, BCLC stage and other clinical parameters were associated with tumor progression in HCC patients." (PMID 36168627, 2022). "It was subsequently demonstrated that the higher the malignant degree of tumor, the lower the expression of ARHGAP24, and its expression levels were dramatically associated with patient survival." (PMID 35812178, 2022). "Our clinical data further confirmed that ARHGAP24 was an independent indicator predicting time to tumor recurrence (TTR)." (PMID 36168627, 2022). "In the current study, we investigated the prognostic value of 64 RhoGAPs using TCGA and GEO databases, and showed that ARHGAP24 was significantly correlated with tumor progression." (PMID 36168627, 2022). "T24 cells transfected with scramble shRNA (sh-NC) and shRNA targeting ARHGAP5, ARHGAP17, and ARHGAP24 were injected into nude mice subcutaneously, and knockdown of these genes significantly reduced BC tumor growth." (PMID 34307347, 2021). "ESTIMATE score demonstrated that high expression levels of LIFR, ARHGAP24, and ELOVL5 were significantly associated with lower tumor purity, whereas CBX3 exerted an inverse effect." (PMID 33463006, 2021). "The ESTIMATE score, combination of stromal and immune score, indicated that high expression levels of LIFR, ARHGAP24, and ELOVL5 were significantly associated with lower tumor purity, whereas CBX3 exerted an inverse effect." (PMID 33463006, 2021). "Moreover, in vitro assays including cell counting kit-8, colony formation, wound healing and Transwell assays, and in vivo tumor growth and pulmonary metastases evaluations were conducted to evaluate the biological function of ARHGAP24 in HCC." (PMID 36168627, 2022). "Mechanistically, miR-21 downregulated ARHGAP24 expression to eliminate its anti-tumor effect." (PMID 35812178, 2022). "Notably, patients with low ARHGAP24 in early tumor stage (BCLC: 0 + A; P < 0.01) or low alpha-fetoprotein subgroups (≤ 400 ng/mL; P < 0.05) also had higher probabilities of tumor progression when compared to the patients with high ARHGAP24." (PMID 36168627, 2022). "Moreover, analysis of liver orthotopic xenograft tumors further confirmed that ARHGAP24 knockdown promoted tumor growth in vivo, as evidenced by increased tumor volume and weight (P < 0.01)." (PMID 36168627, 2022). "Conversely, the volumes of tumor xenografts derived from HCCLM3 vector control and HCCLM3 ARHGAP24 overexpressing cells were 1845.22 ± 152.17 and 398.25 ± 73.89 mm3, respectively (P < 0.01), suggesting that ARHGAP24 overexpression markedly inhibited tumor growth." (PMID 36168627, 2022). "Furthermore, ARHGAP24 was a target of miR-21 and acted as a tumor suppressor in PDAC." (PMID 35812178, 2022). "Notably, the tumor suppressor role of WWP1 in HCC was mediated by ARHGAP24 expression." (PMID 36168627, 2022). "Circ-LMO7 exerts as a tumor suppressor in OS, and the circ-LMO7/miR-21-5P/ARHGAP24 axis is involved in OS progression." (PMID 38742566, 2024). "FilGAP (ARHGAP24), a Rac-specific GTPase-activating protein (GAP), suppresses lamellipodia formation, and controls tumor cell migration." (PMID 38426123, 2024). "Mechanistically, miR-21 directly regulated the expression of Rho GTPase activating protein 24 (ARHGAP24), which was indicated to be a tumor suppressor gene." (PMID 35812178, 2022).